MTOR (mechanistic target of rapamycin kinase)
Diseases named in the same sentence as MTOR in open-access papers (continued):
Sharing a sentence is not in itself a finding about the gene and the disease.
neuroblastoma (continued). "Firstly, the half maximal inhibitory concentration (IC50) of four different ATP competitive mTOR inhibitors was determined by performing MTT assays for the neuroblastoma (NB) cell lines Kelly and IMR-32." (PMID 33390782, 2021). "Specifically for neuroblastoma numerous studies have shown that targeting the PI3K/AKT/mTOR signaling pathway is a valid treatment option for aggressive neuroblastoma and decreased proliferation in vitro and reduced tumor growth in vivo." (PMID 33390782, 2021). "Rapamycin/sirolimus is a well-known mTOR inhibitor with reported therapeutic efficacy on aggressive MYCN amplified neuroblastomas." (PMID 34199959, 2021). "Different studies demonstrated that the PI3K/AKT/mTOR pathway plays an important role in neuroblastoma pathogenesis and inhibition of this signaling pathway by mTOR inhibitors were effective in neuroblastoma models." (PMID 33390782, 2021). "PI3K/Akt/mTOR inhibitors represent a potential effective class of compounds targeting hypoxia in neuroblastoma." (PMID 34199959, 2021). "In patients with high-risk neuroblastoma, the therapies targeting PI3K/Akt/mTOR signaling have limitations." (PMID 34041015, 2021). "Concluding, the combination treatment with Dasatinib and Torin-2 instead of Rapamycin revealed an increased mTOR pathway inhibition in neuroblastoma cells." (PMID 33390782, 2021). "OXY has been previously reported to be capable of inducing neuroblastoma cell death by autophagy via the PI3K/AKT/mTOR pathway." (PMID 34305605, 2021). "OxyR has previously been reported to activate autophagy in neuroblastoma cells via an mTOR-dependent pathway." (PMID 33800526, 2021). "It has been shown that inhibiting PI3K/AKT/mTOR signaling cascade induces downregulation of MycN expression and reduces the growth of neuroblastoma cells in vitro and in vivo." (PMID 33390782, 2021). "In neuroblastoma cells induced to express mutant Htt polyQ72 fragments, catalytic inhibitors of total mTOR or mTOR specific siRNA, induced autophagy and reduced protein aggregates." (PMID 34215308, 2021). "The dual PI3K/mTOR inhibitor PI-103-treated neuroblastoma cells have been reported to activate FOXO3a and trigger apoptosis." (PMID 34685502, 2021). "In an in vitro study, extracellular MANF was shown to protect human neuroblastoma SH-SY5Y cells from 6-hydroxydopamine (6-OHDA) induced cell death via the activation of PI3K/Akt/mTOR pathway." (PMID 33071755, 2020). "Understanding the PI3K/Akt/mTOR pathway in METH-treated neuroblastoma cells is pivotal for establishing novel therapeutics against side effects of METH." (PMID 32120831, 2020). "Simultaneous targeting of PIM, PI3K, and mTOR is an effective strategy to induce differentiation, cell death, and reduced tumor growth in neuroblastoma." (PMID 31310053, 2019). "Screening IBL‐302 in over 700 cell lines representing 47 tumor types identified neuroblastoma as a strong candidate for PIM/PI3K/mTOR inhibition." (PMID 31310053, 2019). "In a therapeutic study of neuroblastoma, the study reported by inhibiting the autophagy via mTOR activation to understand the role of autophagy in the treatment of METH-induced cell death." (PMID 30717078, 2019). "Previous studies have shown that the PI3K/AKT/mTOR signalling cascade is overactivated in neuroblastoma." (PMID 31511046, 2019). "As we demonstrated, the Akt/mTOR signalling pathway also seems to play an important role in the effect of GBE on neurite outgrowth of human neuroblastoma cells (SH-SY5Y cells)." (PMID 31790465, 2019). "This above mTOR activated autophagy inhibition has been shown to reduce cell death in human neuroblastoma SK-N-SH cells." (PMID 30717078, 2019). "Taken together, the RNA, protein, and phospho‐protein data show that the signaling of PIM, PI3K, and mTOR seems to be of importance for regulating neuroblastoma cell apoptosis." (PMID 31310053, 2019). "Here, we investigated the use of novel multikinase PIM/PI3K/mTOR inhibitors in neuroblastoma treatment." (PMID 31310053, 2019).
neuroblastoma (continued). "Triple PIM/PI3K/mTOR inhibition induced differentiation of neuroblastoma cells, increasing the expression of the sympathetic neuronal marker Gap43 and promoting neurite outgrowth." (PMID 31310053, 2019). "In vitro treatment of neuroblastoma cancer cells with mTOR inhibitor (rapamycin) directly differentiates them into osteoblastic and hepatic lineage causing a reversal state of the tumor cells." (PMID 31191243, 2019). "Inhibition of PI3K and/or of its downstream effector mammalian target of rapamycin (mTOR) has shown promising results in multiple preclinical cancer models, including childhood cancer neuroblastoma." (PMID 31310053, 2019). "We developed multikinase PIM/PI3K/mTOR inhibitors, and among > 700 cancer cell lines of various origin, neuroblastoma was particularly sensitive toward the triple kinase inhibitor IBL‐302." (PMID 31310053, 2019). "This work builds on previous and current recent studies from our and other labs that evaluate the effect of different Akt and mTOR inhibitors on neuroblastoma and glioblastoma tumors." (PMID 30323898, 2018). "Further studies in neuroblastoma preclinical models have confirmed a role for the PI-3 kinase/AKT/mTOR pathway in neuroblastoma pathogenesis." (PMID 30384486, 2018). "Early studies also determined that mTOR inhibitors were effective in neuroblastoma models, and one of two patients with relapsed neuroblastoma had a CR in initial phase I studies with the mTOR inhibitor temsirolimus." (PMID 30384486, 2018). "Afatinib also induced apoptosis and blocked EGF-induced activation of PI3K/AKT/mTOR signaling in all neuroblastoma cell lines tested." (PMID 27902463, 2017). "Further mechanistic studies revealed that CHERP depletion induces ERS and CHOP-dependent DR5 transcription; attenuates AKT, mTOR and 4EBP1 phosphorylation; and ultimately promotes neuroblastoma cell apoptosis." (PMID 29113358, 2017). "In this study a time-dependent effect of PI3K/mTOR inhibition on doxorubicin-induced apoptosis in neuroblastoma cells was observed." (PMID 27302920, 2017). "In brief, CHERP depletion induces ER stress and CHOP-dependent DR5 transcription, attenuates mTOR and 4EBP1 phosphorylation, and ultimately induces neuroblastoma cell apoptosis." (PMID 29113358, 2017). "Rigacci and collaborators have recently proposed that OLE induces autophagy via the AMPK/mTOR cascade in neuroblastoma cells as well as in a mouse model of AD." (PMID 27517912, 2016). "We show that PI3K/mTOR inhibitors selectively killed MYCN-expressing neuroblastoma tumor cells, and induced significant apoptosis of transgenic MYCN-driven neuroblastoma tumors concomitant with elimination of MYCN protein in vivo." (PMID 27438153, 2016). "In our study, we demonstrate that inhibition of the mTOR pathway by Everolimus alone is sufficient to block cell growth in NRAS mutant neuroblastoma cells compared to wild type cells." (PMID 26821351, 2016). "Given the modest activity of both groups of mTOR inhibitors against neuroblastoma and this feedback loop, researchers have turned to dual inhibitors targeting both PI3K and mTOR." (PMID 26771642, 2016). "The enhanced sensitivity of MYCN overexpressing neuroblastoma cell lines to PI3K/mTOR inhibition is somewhat surprising, since these cells lack intrinsic mutations in the PI3K pathway members PTEN or PIK3CA." (PMID 27438153, 2016). "Evidence suggests that certain oncogenic pathways and cell cycle regulators such as NF-kB, PI3K/mTOR, hedgehog and polo-like kinase 1 (PLK1) are overexpressed and activated in high risk neuroblastoma." (PMID 26934655, 2016). "SF1126, another dual PI3K/mTOR inhibitor, has been demonstrated to inhibit neuroblastoma cell proliferation." (PMID 26771642, 2016). "Strikingly, inhibition of the mTOR pathway alone resulted in a strong blockage of cell growth in NRAS mutant neuroblastoma cancer cell lines compared to wild-type." (PMID 26821351, 2016).
neuroblastoma (continued). "Western blot data clearly showed that all inhibitors as single agents, significantly downregulated the levels of phosphorylated p65 (NF-kB) and S6K (mTOR) molecules in all three neuroblastoma cells." (PMID 26934655, 2016). "Similar to rapamycin, the ATP-competitive mTOR inhibitors appear to have limited activity against neuroblastoma cell proliferation." (PMID 26771642, 2016). "The use of mTOR/AKT inhibitors along with ALK inhibitors have also been recently justified in ALK-altered neuroblastoma." (PMID 26384210, 2015). "Inhibitors of PI3K/Akt signaling and mTOR have previously been shown to affect Mycn protein expression in neuroblastoma cells." (PMID 24759734, 2014). "In neuroblastoma, mTOR/S6K1 signaling is known to have a role in the development of this disease and recent evidence also implicates the HH pathway." (PMID 25134527, 2014). "Previous reports have suggested that neuroblastoma cell lines expressing high levels of MYCN were significantly more sensitive to mTOR inhibitors compared with cell lines expressing low MYCN levels." (PMID 24391509, 2014). "Other such pathways that were highly represented in the NB10 cells included the ERK/MAPK and mTor signaling pathways, which are known to play a role in neuroblastoma tumorigenesis." (PMID 24349301, 2013). "Here we show that targeted therapy using the PI3K/mTOR inhibitor NVP-BEZ235 significantly enhances doxorubicin-induced apoptosis in neuroblastoma cells." (PMID 24391739, 2013). "Analysis of the mechanisms of action revealed that R1507 inhibits cell growth by attenuation of the AKT/mTOR signaling pathway in neuroblastoma and medulloblastoma cells." (PMID 23056595, 2012). "Therefore, mTOR represents a significant therapeutic target for various cancers, including neuroblastoma." (PMID 40445424, 2025). "A phase I/II study of crizotinib in combination with another mTOR inhibitor, temsirolimus, in relapsed or refractory neuroblastoma with ALK or MET aberrations is currently ongoing, although unexpected toxicity caused by temsirolimus was detected (EUCTR2015-005437-53)." (PMID 41511287, 2025). "Thus, we have questioned if CQ and CQR-mediated inhibition of p-mTOR (the active form of mTOR protein) results in the down-regulation of protein biosynthesis in neuroblastoma cells." (PMID 41304961, 2025). "Furthermore, phosphorylation of mTOR at Ser2448 and P70-S6K at Thr389, signs of mTORC1 pathway activation, increased in neuroblastoma cells after ectopic DDX1 expression." (PMID 38197697, 2024). "In addition, signaling through the IGF1R/PI3 kinase/AKT/mTOR pathway facilitates neuroblastoma metastasis to bone and induces resistance to cytotoxic chemotherapy, retinoic acid, and ALK inhibitors." (PMID 39001383, 2024). "Given AKT and mTOR’s known role in cancer cell migration, immunoblotting was used to evaluate whether P-Rex1 affects AKT and mTOR activity in neuroblastoma." (PMID 38884093, 2024). "In neuroblastoma, the PI3/Akt/mTOR pathway has been found to affect multiple pathways/proteins to enhance the neuroblastoma phenotype, such as stabilizing MYCN, which in turn facilitates processes associated with malignancy like proliferation, angiogenesis, and metabolic reprogramming." (PMID 39319058, 2024). "Previous research revealed that rap inhibits neuroblastoma cell proliferation by reducing MYCN protein expression, which may be associated with the PI3K/AKT/mTOR pathway." (PMID 36978413, 2023). "Specifically, we found that Pon1 depletion downregulated histone demethylase Phf8 both at the protein and mRNA level, increased H4K20me1 binding at the mTOR promotor, and upregulated mTOR expression and phosphorylation in the mouse brain and neuroblastoma N2a-APPswe cells." (PMID 36899882, 2023). "In MYCN-related mice models, phosphatidylinositol 3-kinase (PI3K)/mTOR pathway inhibition is reported to destabilize N-Myc and be effective against tumors, while other studies have reported that N-Myc could regulate the mTOR pathway in neuroblastoma." (PMID 35490242, 2022).
neuroblastoma (continued). "Astemizole, an H1 histamine receptor antagonist, has the capacity to inhibit mTOR signaling and is able to prevent PrPSc replication in a persistently infected neuroblastoma cell line, prolonging the survival of mice infected with intracerebral inoculation of RML scrapie prion." (PMID 36148145, 2022). "Therefore, the use of mTOR pathway inhibitors in combination with other agents for neuroblastoma therapy has been proposed." (PMID 35490242, 2022). "Moreover, we found that neuroblastoma had the highest level of mRNA expression of mTOR pathway genes, and that BGA002 led to mTOR pathway inhibition followed by autophagy reactivation in MNA-NB cells, which was strengthened by BGA002-RA." (PMID 35490242, 2022). "In addition, it was demonstrated that rapamycin inhibits cell proliferation and induces autophagy in human neuroblastoma cell lines by suppressing the mTOR signaling pathway through increasing gene expression of LC3-II/LC3-I and Beclin." (PMID 36185289, 2022). "Furthermore, compared with classical parameters, here we showed that the survival of neuroblastoma patients can be more efficiently predicted by combining mTOR activity, MYCN-status, and differentiation." (PMID 35490242, 2022). "INSM2 as a super-enhancer-associated gene could regulates lipid metabolism by modulating mTOR signaling pathway in neuroblastoma." (PMID 36114560, 2022). "PI3K/Akt/mTOR inhibitors may thus find future applicability as a new adjuvant therapy in randomized clinical trials involving neuroblastoma patients with hypoxic tumors." (PMID 34199959, 2021). "This study suggests that SP141 warrants further investigation as an MDM2 antagonist, particularly in combination with other agents currently used to treat neuroblastoma, such as mTOR or ALK inhibitors, to provide improved anticancer activity against neuroblastomas with different genetic backgrounds." (PMID 33291373, 2020). "Autophagy activity could be suppressed by the mammalian target of rapamycin (mTOR), an atypical serine/threonine protein kinase, and the expression of mTOR gene was decreased in neuronal mouse neuroblastoma differentiation." (PMID 30800669, 2019). "Our combined PIM/PI3K/mTOR inhibition is a viable treatment strategy for neuroblastoma." (PMID 31310053, 2019). "A recent study indicates that alectinib could suppress cell proliferation and induce apoptosis through the inhibition of PI3K/Akt/mTOR signaling in neuroblastoma cells." (PMID 29716528, 2018). "Moreover, afatinib exhibits anti-tumor efficacy by inducing apoptosis and blocking the PI3K/AKT/mTOR signaling in a neuroblastoma xenograft mouse model." (PMID 29716528, 2018). "The role of mTOR/S6K signalling in the formation of tau hyperphosphorylation has been previously studied in several model systems such as human SH-SY5Y neuroblastoma cells and mouse neuroblastoma 2a (N2a) cells, primary cortical neurons and metabolically active brain slices." (PMID 28489581, 2017). "It has been reported that LMNA mutation activates AKT mTOR signaling and impairs autophagy, which results in cell damage that causes laminopathies, and down-regulation of the LMNA gene in neuroblastoma promotes tumor progression." (PMID 30460069, 2017). "Interestingly, combination of MEK and mTOR inhibitors is synergistic in NRAS mutant neuroblastoma cell lines which were observed for both cell lines." (PMID 26821351, 2016). "Therefore, to identify a most efficacious treatment for neuroblastoma, we investigated the efficacy of NF-kB/mTOR dual-inhibitor 13-197, hedgehog inhibitor vismodegib and PLK1 inhibitor BI2536 alone or combined with topotecan against high-risk neuroblastoma." (PMID 26934655, 2016).
neuroblastoma (continued). "Similarly, Hcy treatment caused significant increases in the level of MTOR phosphorylation and its downstream substrates RPS6KB1/p70S6K and EIF4EBP1 in human neuroblastoma SH-SY5Y cells." (PMID 27929536, 2016). "However, these inhibitors decreased the levels of phosphorylated S6K and 4E-BP1 molecules of the mTOR pathway compared to vehicle treated neuroblastoma cell lines, suggesting that BI2536 and vismodegib can also target the mTOR signaling pathway." (PMID 26934655, 2016). "In addition, overexpression and activation of the key cellular pathways such as NF-kB, mTOR, hedgehog and PLK1 molecules are associated with resistance to therapy in neuroblastoma." (PMID 26934655, 2016). "NVP-BEZ235, a potent inhibitor of both PI3K and mTOR-kinases, which is already in clinical trials for PI3K pathway-mutated adult cancers, eliminated intra-tumoral MYCN and induced regression of MYCN-driven transgenic neuroblastoma tumors in vivo." (PMID 27438153, 2016). "However, there was no significant change observed on the expression of these molecules in non-MYCN amplified neuroblastoma cells, suggesting combination specificity to MYCN-amplified neuroblastoma cells targeting NF-kB and mTOR pathways." (PMID 26934655, 2016). "By broadening in vivo and cell line studies across this new pharmacologic scaffold, these studies add to the growing evidence implicating PI3K/mTOR inhibition as a viable strategy in MYCN-driven pediatric cancers including both neuroblastoma and medulloblastoma." (PMID 26029667, 2015). "We have previously shown efficacy for the PI3K/mTOR inhibitor BEZ235 in neuroblastoma." (PMID 26029667, 2015). "Furthermore, the phosphorylated and activated form of S6K1 (T389) is decreased after treatment with the mTOR inhibitors rapamycin or CCI-779 in neuroblastoma cells." (PMID 25134527, 2014). "Phosphopeptides from both were more highly abundant in NB10, which may indicate upregulation of mTor activity in these neuroblastoma cells." (PMID 24349301, 2013). "Indeed, treatments of mouse neuroblastoma cells with individual metabolites that accumulate in HHcy, Hcy-thiolactone or N-Hcy-protein recapitulated changes in the Phf8 → H4K20me1 → mTOR → autophagy pathway and Aβ accumulation seen in Blmh-depleted or Met-supplemented HHcy wild-type mice." (PMID 39125665, 2024). "Therefore, therapeutic targeting of PI3K/Akt/mTOR may offer a promising approach for the design of targeted molecular therapies in neuroblastoma." (PMID 36978413, 2023). "Therefore, therapeutic targeting of PI3K/AKT/mTOR may offer a promising approach for the design of molecularly targeted therapies in neuroblastoma." (PMID 37370314, 2023). "Indeed, as we also found in the present study, treatments with Hcy-thiolactone or N-Hcy-protein induce changes in the Phf8->H4K20me1->mTOR->autophagy pathway and Aβ accumulation in mouse neuroblastoma cells like those seen in Blmh-/- mice or mice fed with high Met diet." (PMID 37718819, 2023). "To elucidate the mechanism by which Pon1 depletion impacts Phf8 and its downstream effects on mTOR, autophagy, and APP, we first examined whether the findings in Pon1−/− mice can be recapitulated in cultured mouse neuroblastoma N2a-APPswe cells that overproduce Aβ from a mutated human APP transgene." (PMID 36899882, 2023). "In addition, several studies proved that inhibiting mTOR signaling to further downregulate cellular protein synthesis could deregulate MYCN-driven proliferation, suggesting that mTOR pathway is another key factor in MYCN-amplified children neuroblastoma." (PMID 35805002, 2022). "Moreover, neuroblastoma and small cell lung cancer clustered together for mTOR gene expression, which could be related to the fact that these two highly aggressive tumors derive from peripheral nervous system cells." (PMID 35490242, 2022).